RNU6-640P (RNA, U6 small nuclear 640, pseudogene)
Gene: Small nuclear RNA gene on chromosome 2 (86,515,204 to 86,515,308, reverse strand). Ensembl gene ENSG00000200563.
Homologues: Orthologues: chimpanzee U6 (100% identical), macaque U6 (90% identical), pig U6 (70% identical), mouse Gm23350 (67% identical). Paralogues in human: RNU6-411P (88% identical), RNU6-333P (87% identical), RNU6-1131P (86% identical), RNU6-38P (86% identical), RNU6-468P (86% identical), RNU6-574P (86% identical), RNU6-1145P (85% identical), RNU6-15P (85% identical), RNU6-20P (85% identical), RNU6-25P (85% identical), RNU6-312P (85% identical), RNU6-41P (85% identical), and 1287 more.